EDN1 (endothelin 1)
Diseases named in the same sentence as EDN1 in open-access papers (continued):
Sharing a sentence is not in itself a finding about the gene and the disease.
endothelial dysfunction (continued). "Beyond its principal effects in glucose-decrease, this drug could reduce endothelial dysfunction, inducing nitric oxide production, activating cellular energy pathways, and reducing the expression of some inflammatory markers as Endothelin 1 (ET-1)." (PMID 34295329, 2021). "Decreased nitric oxide production and increased production of endothelin-1 (ET-1) in the vascular wall may promote oxidative stress and low-grade inflammation, with the development of endothelial dysfunction (ED) and increased vasoconstrictor activity." (PMID 34575135, 2021). "Microvascular abnormalities have been demonstrated in diabetes as a consequence of endothelial dysfunction, upregulation of endothelin-1 (ET-1) and downregulation of nitric oxide (NO), autonomic neuropathy, which can result in a reduction in coronary blood reserve." (PMID 34205870, 2021). "PGP generated by the sequential action of MMPs (e.g., MMP9) and PE-mediated degradation of collagen can activate CXCR2 on a variety of cell types, and it has been described as a mediator of endothelial dysfunction owing to increased endothelial permeability and endothelin-1 (ET-1) production." (PMID 33571164, 2021). "In addition, persistent endothelial dysfunction, including those manifested by a stable increase in the level of endothelin-1 in the blood plasma, also contributes to vasospasm, and, indirectly, to the progression of fibrotic changes in the vascular wall." (PMID 33498971, 2021). "Because of the instability of ET-1 at room temperature and its rapid clearance from circulation, the more stable precursor fragment of ET-1, called C-terminal proendothelin-1 (proET-1), which can be measured by a sandwich immunoassay, is the preferable biomarker to assess endothelial dysfunction." (PMID 33985491, 2021). "Fourth, in vitro analysis indicates that high TG might also promote endothelial dysfunction, by stimulating the expression of endothelial mediators, such as endothelin-1." (PMID 32669093, 2020). "Normal VEGF signaling mediates endothelial homeostasis, and VEGF inhibition leads to endothelial dysfunction, stimulating the release of Endothelin-1 (ET-1), a potent vasoconstrictor that may play a role in mediating hypertension." (PMID 33081013, 2020). "CRP was reported to be effective on endothelial dysfunction in a way that high levels may reduce nitric oxide production, increase endothelin 1, and up-regulate angiotensin type 1 receptor, therefore, influencing on renin-angiotensin-aldosterone system." (PMID 32489776, 2020). "In this study, HT treatment (10 μM for 48 h) induced a significant up-regulation of endothelin-1 (ET-1) and eNOS phosphorylation, as well as NO production, being effective in the protection against endothelial dysfunction, induced by high glucose and free fatty acids." (PMID 32825589, 2020). "Circulating biomarkers such as endothelin-1, E- and P-selectins, vWF and soluble adhesion molecules that signify endothelial dysfunction may appear as early biomarkers of viral infection and probable organ dysfunction." (PMID 32848893, 2020). "In this regard, we have shown that endothelial dysfunction and endothelin-1 dysregulation are important and may represent potential therapeutic targets for patients with symptoms and/or signs of ischemia and no obstructive CAD." (PMID 31709984, 2020). "The consequences of 25[OH]D deficiency and elevated PTH levels are calcium loading, with cardiomyocyte and skeletal muscle contractile dysfunction, cellular hypertrophy, oxidative stress, immune activation, endothelial dysfunction (including enhanced endothelin-1 release)." (PMID 30121806, 2019). "Endothelial dysfunction is the main trigger for the release of endothelin-1." (PMID 31027378, 2019).
endothelial dysfunction (continued). "Vasopressin contributes to vasoconstriction by different mechanisms: stimulation of the renin–angiotensin–aldosteron system (RAAS), direct effect on smooth muscle cells, or via secretion of endothelin-1 (ET-1) from endothelial cells, which aggravates endothelial dysfunction." (PMID 31187425, 2019). "During insulin-resistant conditions, pathway-specific impairment in PI3K-dependent signaling may cause imbalance between production of nitric oxide (NO) and secretion of endothelin-1 and lead to endothelial dysfunction." (PMID 29588341, 2018). "Many studies have reported that endothelial dysfunction resulting from an imbalance of vasoactive substances, including endothelin 1 (ET-1), as well as neuronal and endothelial nitric oxide synthases (nNOS and eNOS) plays a role in the pathophysiology of several ischemic conditions." (PMID 30524661, 2018). "PPARα and PPARγ mRNA are greater in young and adult SHR mesenteric arteries compared to WKY (but not in other tissues), and thizaolidinedione PPARγ agonists attenuated remodeling and endothelial dysfunction in mesenteric resistance arteries in response to angiotensin II or endothelin-1." (PMID 28264510, 2017). "Accordingly experimental studies demonstrated a cocaine-induced endothelial dysfunction with a decrease in NO release and in the constitutive enzyme NO-synthase (eNOS) content, as well as an increase in endothelin-1 (ET-1) production and ET-1 receptor type-A (ETAR) protein expression." (PMID 26823954, 2016). "Higher levels of CRP may increase blood pressure by reducing nitric oxide production in endothelial cells, resulting in vasoconstriction and increased production of endothelin-1 which are the markers for endothelial dysfunction." (PMID 26989902, 2016). "In addition, endothelial dysfunction, another major contributor to CIN progression, is caused by a nitric oxide (NO) and endothelin-1 imbalance, after CM exposure." (PMID 25357250, 2014). "IR may impair the PI3K-dependent signaling, alter the balance between NO and endothelin-1 towards diminished insulin-induced vasodilation or even vasoconstriction leading to exacerbated IR and endothelial dysfunction." (PMID 24391852, 2013). "Endothelin-1 enhances CVD by endothelial dysfunction and hypertension." (PMID 23193471, 2012). "It led to an increase in nephrin expression, improvement of the endothelial dysfunction due to decreases in endothelin 1 (ET-1) and plasminogen activator inhibitor 1 (PAI-1), and an increase in endothelial nitric oxide synthase (eNOS) expression in the renal cortex." (PMID 22567283, 2012). "Interestingly, mice subjected to the AFD regimen displayed downregulated expression levels of the endothelial dysfunction marker endothelin-1, the inflammatory markers MCP-1 and CD68 and the fibrosis markers desmin when compared to HFD fed mice." (PMID 23049881, 2012). "Thus the combination of raised sFlt1 and sEng appears to impair nitric oxide generation and activate endothelin-1 signaling with hypertension and aggravation of maternal endothelial dysfunction." (PMID 22848831, 2012). "Hence, in endothelial dysfunction where NO is downregulated and endothelin-1 upregulated, the balance is shifted in favor of increased arterial stiffness." (PMID 21915370, 2011). "Additionally, a reduction in biochemical markers intracellular adhesion molecule-1 (ICAM-1) and endothelin-1 (ET-1) were seen in the intervention group, both indicators of inflammation and endothelial dysfunction, further supporting the proposed mechanism of action of ischaemic conditioning." (PMID 39702489, 2024). "Increased sympathetic receptor activation in blood vessels, endothelial dysfunction, increased concentration of endothelin-1 (ET-1), and various anomalies in the central thermoregulatory system have been hypothesized to be potential contributors to the development of primary RP25." (PMID 38719920, 2024).
endothelial dysfunction (continued). "Furthermore, dietary potassium lowers endothelin-1 levels, which may reverse endothelial dysfunction brought on by a high-salt diet, contributing to this positive effect." (PMID 38381721, 2024). "Notably, it is hypothesized HCQ may influence CT by modulating vasoconstriction and endothelial dysfunction mediated by endothelin-1." (PMID 37041478, 2023). "Furthermore, insulin resistance in ECs with the stimulation of phosphoinositide 3-kinase (P13K)/Akt and endothelial nitric oxide (NO) synthase (eNOS) pathway is attributed to decreased NO production and increased endothelin-1 (ET-1) secretion, promoting endothelial dysfunction." (PMID 35742837, 2022). "Endothelial dysfunction may also precede the development of hypertension by contributing to increased peripheral resistance, i.e., through activation of the renin–angiotensin system, endothelin-1, catecholamines, and growth factors’ production." (PMID 36364796, 2022). "Endothelial dysfunction is mainly reflected in the reduction of vasodilators such as nitric oxide (NO) bioavailability and increased levels of vasoconstrictive substances, such as endothelin-1 (ET-1), angiotensin II, prostaglandin H2, reactive oxygen species (ROS) and so on." (PMID 36292919, 2022). "In addition, selective insulin resistance in the phosphoinositide 3-kinase/Akt/endothelial nitric oxide (NO) synthase pathway in endothelial cells is involved in decreased NO production and increased endothelin-1 production from the endothelium, resulting in endothelial dysfunction." (PMID 34439553, 2021). "Finally, there are known causal associations between low adiponectin and insulin resistance, which we show evidence of in schizophrenia, as well as between low adiponectin and endothelial dysfunction, and indeed we find that endothelin-1 is significantly elevated in schizophrenia." (PMID 34873143, 2021). "There is a strong association between endothelial dysfunction and CVD, as exemplified by concurrent decreased formation and/or bioactivity of the vasodilator nitric oxide and increased levels and/or activity of the endothelial-derived vasoconstrictor endothelin-1 (ET-1)." (PMID 32309625, 2019). "Furthermore, we could support that multiple products, other than endothelin-1, derived by severe acidosis, possibly contribute to endothelial dysfunction, resulting in elevated vascular resistance and intradialytic hypertension." (PMID 29850223, 2018). "Also, TNF-α and other inflammatory factors induce systemic endothelial dysfunction, including increased endothelin-1 release, induction of oxidative stress, and enhanced sensitivity to angiotensin II (AngII), which combine to exacerbate the maternal hypertension." (PMID 25249978, 2014). "Moreover, we focused primarily on inflammatory and hematologic indices; the addition of emerging markers of endothelial dysfunction (e.g., endothelin-1, von Willebrand factor) or systemic inflammation (e.g., interleukin-6, C-reactive protein) may enhance prognostic stratification." (PMID 41303423, 2025). "Furthermore, endothelial dysfunction exacerbates atherogenesis through the dysregulation of vasoactive substances, characterized by diminished NO bioavailability and altered endothelin-1 (ET-1) secretion, coupled with enhanced platelet activation and prothrombotic tendency." (PMID 40689206, 2025). "Endothelial dysfunction and increased blood pressure were more pronounced in nano-SPM-exposed mice, also supported by elevated endothelin-1 and reduced endothelial nitric oxide synthase expression, which enhances constriction and diminishes vasodilation." (PMID 40319735, 2025). "EDN1 promotes the generation of reactive oxygen species (ROS) by activating NADPH oxidase, leading to increased oxidative stress, endothelial dysfunction, and vascular remodeling." (PMID 40051702, 2025).
endothelial dysfunction (continued). "Studies have demonstrated that IR-related endothelial dysfunction disrupts the balance between the PI3K-NO vasodilatory pathway and the MAPK-endothelin-1 vasoconstrictive pathway, leading to impaired vascular homeostasis." (PMID 41584289, 2025). "Using pathway analysis, we found that 5 of these AhR-dependent miRNA appear to play roles in modulating the endothelin-1 and endothelial nitric oxide signaling pathways, two pathways important in EPFR-induced endothelial dysfunction." (PMID 40214911, 2025). "Likewise, there is an inflammatory endothelial dysregulation in COVID-19 patients during the acute phase, characterized by elevated levels of biomarkers of endothelial dysfunction, such as endothelin-1 (ET-1), which could produce long-term vascular involvement." (PMID 40336917, 2025). "Plasma levels of nitrite, big endothelin-1, asymmetric dimethylarginine (ADMA), presepsin, and claudin were measured as biomarkers of endothelial dysfunction, bacterial translocation, and intestinal barrier dysfunction." (PMID 38396668, 2024). "In contrast, IR leads to endothelial dysfunction with impaired PI3K and increased MAPK-related endothelin 1 secretion." (PMID 38025203, 2023). "In cultured ECs, miR-483 targets a number of endothelial dysfunction-related genes, such as transforming growth factor-β (TGF-β), connective tissue growth factor (CTGF), angiotensin-converting enzyme 1 (ACE1), and endothelin-1 (ET-1)." (PMID 35222797, 2022). "Different pro-oxidant molecules are involved in endothelial dysfunctions, including NOX enzymes, xanthine oxidase, mitochondrial enzymes, lipoxygenase, myeloperoxidase, endothelial NOS (eNOS), iNOS, and endothelin-1 (ET-1) peptide." (PMID 36139904, 2022). "The effect of DPI on endothelial dysfunction as represented by the CAR response, CAR%, and plasma endothelin-1 levels." (PMID 36277757, 2022). "Endothelin 1 (ET-1) and vascular cell adhesion molecule 1 (VCAM-1) are markers of endothelial dysfunction that are also elevated in preeclampsia." (PMID 33919808, 2021). "Endothelial dysfunction as measured by reflection index (RI), biomarkers of oxidative stress (NO, MDA, and glutathione), and inflammation (hsCRP, endothelin-1, ICAM-1, and VCAM-1) were evaluated at baseline, 4, and 12 weeks." (PMID 34257675, 2021). "In adult Wistar rats, PARP enzyme is activated in the endothelium after endothelin-1 (ET-1) incubation, and PJ34 counteracts ET-1-induced endothelial dysfunction." (PMID 32911782, 2020). "PPB or ECE attenuated endothelial dysfunction by enhancing the pAMPK-PI3K-peNOS pathway and reducing the expression of endothelin-1 (ET-1)." (PMID 31731817, 2019). "Evidence of endothelial dysfunction was observed in NTG patients, including higher basal plasma endothelin-1 and abnormal endothelin-1 response to laboratory stimuli." (PMID 29879162, 2018). "Interestingly, these beneficial effects of androstenediol on intrahepatic hemodynamics are due to induction of eNOS-mediated NO and a decrease in endothelin-1, which may also represent a potential remedy for endothelial dysfunction in the microcirculation of cirrhotic liver." (PMID 28810889, 2017). "Signaling of a receptor for endothelin-1, EDNRA, mediates activation and proliferation of VSMC, and its selective inhibitors prevent endothelial dysfunction, structural vascular change in atherosclerosis, and also inhibit cholesterol induced atherosclerosis." (PMID 26488411, 2015). "Endothelial dysfunction and increased activity of NADPH oxidase were described in mice overexpressing preproendothelin-1 in the endothelium." (PMID 21915370, 2011). "Additionally, endothelial dysfunction is a key event in IR-related CVD, characterized by reduced nitric oxide (NO) bioavailability and increased endothelin-1 secretion, leading to an imbalance between vasodilation and vasoconstriction." (PMID 40313486, 2025).
endothelial dysfunction (continued). "The endothelial dysfunction occurring in HTS contributes to fibroblast inhibition and scar regression, and reduced TGF-β1, PDGF, and basic FGF levels played more important roles in these processes than VEGF and endothelin 1 (ET-1)." (PMID 38731893, 2024). "Therefore, vasomotor endothelial dysfunction involving ADMA and endothelin-1 plays an equal role in the formation of both CHD with and without ICMP and is not a key factor in the ICMP pathogenesis." (PMID 37509589, 2023). "Despite a large pool of interesting candidate biomarkers, endothelin-1 (ET-1) appears to be involved in multiple aspects of AHF pathogenesis that include neurohormonal activation, cardiac remodeling, endothelial dysfunction, inflammation, atherosclerosis and alteration of the renal function." (PMID 37443671, 2023). "This may be partially attributed to the prevalence of endothelial dysfunction in this population, manifested by lower flow-mediated dilation (FMD), thicker cIMT, and higher endothelin-1 levels (ET-1), a potent constrictor, compared to CA counterparts." (PMID 37834170, 2023). "Endothelin-1 (EDN1) has been investigated as responsible for CMD and endothelial dysfunction." (PMID 35330036, 2022). "Here, we directly compared both esomeprazole MH and MTH and examined whether esomeprazole MTH can also mediate endothelial dysfunction by examining markers of dysfunction (vascular cell adhesion molecule-1 (VCAM-1) and endothelin-1 (ET-1))." (PMID 36076929, 2022). "Without an upregulation of endothelial nitric oxide, endothelin-1 (ET-1) production is likely uninhibited, and systemic inflammation and endothelial dysfunction ensues." (PMID 34362171, 2021). "Endothelial dysfunction of vessels was characterized by increased blood levels of vascular endothelial growth factor (VEGF), endothelin-1 (ET-1), P-selectin (PSel), homocysteine (Hcys), nitrites (NO2), and cyclic guanosine monophosphate (cGMP), as well as decreased PGI2 values." (PMID 34833133, 2021). "Other authors have shown attenuating in vitro effects of urolithin A on endothelial dysfunctions induced by oxidized LDL through the beneficial modulation of TNF-α, IL-6, endothelin 1, PPAR-γ, ICAM-1 (intercellular adhesion molecule 1), and MCP-1 (monocyte chemotactic protein 1) expression." (PMID 33322602, 2020). "In healthy men, higher expression and bioactivity of vasoconstrictors such as endothelin-1 but not vasodilators such as eNOS, contribute to impaired endothelial dysfunction with aging." (PMID 31370219, 2019). "Endothelial dysfunction in PAH is characterized by a reduced production of vasodilatators prostacyclin and nitric oxide (NO) and an increased production of endothelin-1 (ET-1), a potent vasoconstrictor: its importance in idiopathic PAH pathology has been widely studied." (PMID 25905096, 2015). "Several other important biomarkers of endothelial dysfunction including Endothelin-1 and von Willebrand factor were not examined." (PMID 24339964, 2013). "Endothelial dysfunction may contribute to reduced CBF due to imbalance between vasodilators (e.g., nitric oxide (NO), bradykinin, and prostacyclin) and vasoconstrictors (e.g., endothelin-1 and thromboxane A2)." (PMID 37238700, 2023). "The overexpression of miR-483-3p in endothelial cells inhibits Ang II-induced endothelial dysfunction by targeting several molecules, such as transforming growth factor-beta (TGF-β), connective tissue growth factor (CTGF), angiotensin-converting enzyme 1 (ACE1), and endothelin-1 (ET-1)." (PMID 37489457, 2023). "Especially, the release of catecholamines such as noradrenaline by sympathetic activation may contribute directly to endothelial dysfunction by direct vasoconstriction via α1-receptor activation as well as downstream activation of RAAS and endothelin-1 pathway." (PMID 36719770, 2023).